ERBB3 (erb-b2 receptor tyrosine kinase 3)
Diseases named in the same sentence as ERBB3 in open-access papers (continued):
Sharing a sentence is not in itself a finding about the gene and the disease.
cancer (continued). "Elevated NRG1 expression and activated ERBB3 are seen in many types of human cancers supporting the rationale to target the NRG1-ERBB3 axis." (PMID 33273014, 2021). "Four proteins (PLAU, ITGA5, ZEB1, and ERBB3) were involved in “microRNAs in cancer” signaling pathway." (PMID 34408977, 2021). "The receptor binding was demonstrated by immunofluorescent confocal microscopy on four different ErbB3+ cancer cell lines." (PMID 34572289, 2021). "To visualize the receptor binding previously established in surface plasmon resonance experiments, we performed immunocytochemical staining of several high ErbB3-expressing cancer cell lines with subsequent imaging by confocal microscopy." (PMID 34572289, 2021). "Overexpression of ERBB3, EZR, and TM9SF2 has been associated with cancer progression, increased proliferation and metastasis or poor survival." (PMID 33690729, 2021). "ERBB3 has gained attention as a potential therapeutic target to treat colorectal and other types of cancers." (PMID 34843459, 2021). "To confirm the relevance of ERBB3 activator function in vivo, and also generate a resource that can be used to further clarify the role of ERBB3 in cancer, we generated activator‐function impaired V943R mutant Erbb3 mice." (PMID 36618440, 2021). "Next, we identified prognostic gene mutations (ATR, ERBB3, KDR, and MUC6), fusions (GOPC-ROS1 and NTRK1-SH2D2A), and VEGF signaling pathway associated with cancer recurrence." (PMID 34599262, 2021). "In ERBB2-driven cancers, ERBB3 enhances cancer progression, usually by PI3K/AKT pathway activation, by functioning as a heterodimer partner." (PMID 34843459, 2021). "Secreted isoforms of ERBB3 have been described in different types of cancer; to the best of our knowledge, only the study by Hsieh and colleagues investigated the accuracy of serum ERBB3 for the detection of HCC." (PMID 33799723, 2021). "The important role of ErbB3 in cancer progression stimulated the development of several monoclonal antibodies to block its aberrant signaling." (PMID 34572289, 2021). "Previous studies have been reported that NRG1 played important roles in cancers by directly binding to ERBB3 or ERBB4 and ERBB3 or ERBB4 interacts with ERBB2 or ligand-receptor, leading to receptor phosphorylation and signal cascade activation." (PMID 34531912, 2021). "PARK7 binds to human epidermal growth factor receptor 3 (ERBB3), a therapeutic anti-cancer target, and increases the stability of ERBB3 by inhibiting its ubiquitination." (PMID 32357493, 2020). "Increased signaling through alternative EGFR family members ERBB2 and ERBB3 has previously been recognized as resistance mechanisms in different types of cancer including NSCLC (65, –67)." (PMID 32234966, 2020). "These include well-known cancer-associated genes, such as CCND1 (25 tumors), CDK4 (25 tumors), MDM2 (23 tumors), SETDB1 (23 tumors), ERBB3 (11 tumors), ERBB2 (11 tumors), MYC (10 tumors) and MYCN (five tumors)." (PMID 32025003, 2020). "Located on human chromosome 12q13.2, the ERBB3 (erb-b2 receptor tyrosine kinase 3) gene is known for its role in cancer." (PMID 32226409, 2020). "In particular, PIK3CA H1047L, ATM R2443Q, and ERBB3 V104M are well-documented substitutions that are found in both cancer and hereditary disease." (PMID 33009502, 2020). "Especially WEE1 (WEE1 G2 checkpoint kinase) is known to be an important cell cycle checkpoint kinase, but also ERBB3 (Erb-B2 receptor tyrosine kinase 3) is important in cancer development and has been identified as a potential target for treatment." (PMID 32252623, 2020).
cancer (continued). "The ERBB family of tyrosine kinase receptors, including EGFR (ERBB1/HER1), ERBB2 (Neu/HER2), ERBB3 (HER3), and ERBB4 (or HER4), has largely been associated with cancer pathogenesis and epithelium-mesenchymal transition (EMT)." (PMID 32316671, 2020). "Many of these cancer types also express erbB3, a second NRG1 receptor that is functionally distinct from erbB4." (PMID 31291965, 2019). "The human epidermal growth factor tyrosine kinase receptor (EGFR/ERBB) family, which includes four members: HER1 (EGFR, ErbB1), HER2 (Neu, ErbB2), HER3 (ErbB3), and HER4 (ErbB4) have been associated with many human cancers." (PMID 31470531, 2019). "EGFR, ERBB3, MMP20, MMP27, MCL1, BCL2A1 and BAK1 appear to be important genes for cancer progression due to their frequent association with recurrent cancer-related genes in women." (PMID 31205821, 2019). "In many cancers, activation of the HER3 (ErbB3) receptor frequently results in strong and aberrant activation of the AKT pathway, a critical oncogenic stimulus that leads to apoptosis resistance." (PMID 31443721, 2019). "This pattern of heterogeneity was similar when considering a broader list of pan-cancer driver genes, with private amplification events seen in ERBB3, RHEB, SOS1, SOS2, and EZH2." (PMID 30348992, 2019). "FLG interacts with MCL1, USP1, C21orf59, MAK, and KIR3DS1 and mucin interacts with ERBB3, SNAI1, TWIST1, TWIST2, and CDH2, all of which, IPA predicted to be associated with cancer." (PMID 31058088, 2019). "ERBB3 is a member of the receptor tyrosine kinase family and is involved in the development of numerous types of human cancer." (PMID 31446897, 2019). "Previous studies reported that NRG1 exerts its effects in cancers by directly binding to ERBB3 or ERBB4 which heterodimerizes with ERBB2 and the ligand-receptor interaction, causes the phosphorylation of receptors and activation of signaling cascades." (PMID 30486894, 2018). "ERBB3 is proto-oncogene and promotes differentiation of undifferentiated cancer cells and plays an important role in cancer formation and are related to a favorable prognosis." (PMID 29301256, 2018). "Of the non-T-cell related targets, the proteins currently most widely targeted are ERBB2 (HER2), EGFR, MS4A1 (CD20), CD22, PDCD1 (PD-1), MSLN (mesothelin), and ERBB3 (Her3), all for cancer indications." (PMID 28822103, 2018). "The cycle involves ERBB3 which has been found to be related to many types of cancer when overexpressed." (PMID 30225028, 2018). "ERBB3 encodes a member of EGFR family receptor tyrosine kinase, which is a well-known gene to be amplified and overexpressed in various cancers." (PMID 30057548, 2018). "These inhibitory AZD6244 concentrations are similar to those reported previously for ERBB3/PI3K/AKT signaling in cancer cells." (PMID 29212253, 2017). "Increasing the expression levels of EGFR family proteins, including EGFR, ErbB2, ErbB3, and ErbB4, can promote the growth of cancer cells." (PMID 29164150, 2017). "A recent interesting study revealed that FGFR-TACC3 fusion protein can promote the resistance of EGFR-dependent cancer cell lines to EGFR/ErbB3 blockage via activation of ERK signaling." (PMID 27956147, 2017). "ErbB3 overexpression is found in a variety of cancers, and plays a role in cancer cell motility and survival." (PMID 28900130, 2017). "The roles of EGFR and ErbB2 in cancer development are presently well established, whereas data on ErbB3 and ErbB4 are still rather fragmentary." (PMID 28417948, 2017). "Together, these results suggest that cancer-free Tasmanian devils have a serum ERBB3 range of <30–663 pg/ml." (PMID 28591206, 2017). "Deleted DNA regions in CD133+ cell population contain known cancer related factors such as ERBB3 (HER3) and HOTAIR." (PMID 28347289, 2017).
cancer (continued). "In the last years it has been demonstrated that ErbB3, another member of the ErbB family receptors, has a key role in the development and progression of several cancers including NSCLC." (PMID 26862736, 2016). "Nevertheless, p-ErbB3 levels declined instantly in response to ErbB2 blockade by both agents, and in most ErbB2-depended cancer cells there was a permanent reduction of p-ErbB3." (PMID 27255951, 2016). "The complex formed by orphan ERBB2 receptor and functionally weak ERBB3 has been recognized as being one of the most mitogenic signaling complexes in cancer development and maintenance." (PMID 26942872, 2016). "Despite the fact that ERBB3 seems to have very little kinase activity, ERBB3 has emerged as an important new therapeutic target in cancer." (PMID 26745281, 2016). "MAPKs are the intracellular effectors of ErbB receptors (EGFR, ErbB2, ErbB3 and ErbB4), and hyperactivation of the ERK1/2 MAPK signaling pathway frequently occurs in human cancer and is associated with increased cell survival and proliferation." (PMID 26843616, 2016). "ErbB2 and ErbB3 form a heterodimer and perform a central role in maintenance and malignancy of lung and other cancers, through activating the phosphatidylinositol-4,5-bisphosphate 3-kinase (PI3K) pathway." (PMID 27480244, 2016). "We found that HDAC inhibitors achieved the EMT reversal and epithelial differentiation effect by restoring E-cadherin and ErbB3 expressions in a panel of cancer cells with an intermediate EMT state." (PMID 27551531, 2016). "Recently, we have generated two ErbB3 monoclonal antibodies (MoAbs), namely A3 and A4, that negatively regulate the ErbB3-mediated signaling pathway, reducing the growth rate of cancer cells from different origins, either in vitro or in vivo." (PMID 26862736, 2016). "Here we clearly provide evidence that the NRG-1β/ErbB-3 axis can induce the cancer stem cell compartment in tumors and induces their clonogenic capacity even in BRAF-V600E mutant CSCs." (PMID 26160848, 2015). "Epidermal growth factor receptor (EGFR) and receptor tyrosine-protein kinase 3 (ErbB3) are two well-established targets in cancer therapy." (PMID 25997020, 2015). "The expression levels of ERBB3 in cancer tissues compared to matched normal tissues were highly variable, ranging from 0.06 to 60.2-fold change respectively." (PMID 26367378, 2015). "At last, ErbB-3-partner interactions were comparably discussed, to provide a clear outline of ErbB-3 signaling in cancer development." (PMID 25993617, 2015). "ErbB3 has a pivotal role in pancreatic tumorigenesis promoting in vitro and in vivo cancer cell proliferation." (PMID 26346854, 2015). "It has been recently described that cancer-associated fibroblasts release NRG1/HRG1 ligand, activating PDAC cells by ErbB3/AKT-mediated signalling and enhancing tumorigenesis." (PMID 26346854, 2015). "As shown in this figure, EGFR and ErbB-3 are primarily expressed in human carcinomas (50% ∼ 70%); ErbB-2 is expressed in 20% ∼ 30% of these carcinomas; and the expression of ErbB-4 occurs only in breast and colon carcinomas." (PMID 25993617, 2015). "While several therapeutic agents against erbB2 and/or EGFR have been used in the treatment of human cancers with efficacy, there has been relatively less emphasis on erbB3 as a molecular target." (PMID 24886126, 2014). "Tumors can become addicted to the oncogenic signaling stimulated by ErbB3 activation, a situation reminiscent of the addiction to Ras and other oncogenes that occurs in other cancers." (PMID 25238142, 2014). "This review summarizes the latest advances in our understanding of the role of erbB3 signaling in cancer development and discusses novel strategies inactivating erbB3 to enhance the efficacy of cancer therapeutics." (PMID 24886126, 2014).
cancer (continued). "In contrast to EGFR and ERBB2, the potency of ERBB3 as a therapeutic target in cancer has only recently been recognized." (PMID 24970817, 2014). "Concomitant inhibition of erbB3 is thought to be required to overcome the resistance and effectively treat cancer patients." (PMID 24886126, 2014). "Recently, the role of erbB3 as an obligate partner and in primary and acquired resistance to cancer therapeutics has attracted considerable attention." (PMID 24886126, 2014). "It inhibits ligand-induced activation of erbB3, and exerts antitumor activity in human cancer models." (PMID 24168763, 2013). "Although ErbB3 has been disregarded for several years as a target for cancer therapies recent meta-analysis of ErbB3 expression in several solid tumor demonstrated that increased levels of receptor are constantly associated with worse survival." (PMID 23890105, 2013). "Amplification of ERBB3 and/or overexpression of its protein has been reported in numerous cancers, including prostate, bladder, and breast." (PMID 23835063, 2013). "Body-wide expression profiles for EPHA2, VEGFC, and ERBB3 indicated the most selective overexpression in malignant connective tissues, when compared to all other pediatric cancer and healthy normal tissues." (PMID 23227212, 2012). "Two cancer cell lines which were more resistant to TE-64562 treatment (EC50 value>30 μM) expressed high ErbB3 (BT-474, Hep-G2)." (PMID 23166750, 2012). "The objective of the authors was to obtain a wider spectrum monoclonal antibody capable of affecting ligand dependent proliferation of cancers which require signaling by EGFR or ErbB3 or both receptors simultaneously." (PMID 22889873, 2012). "Analyses using the miRanda and Pic Tar algorithms indicated that several cancer-associated genes including MMP11, ERBB2, ERBB3, EDN1, VEGF-A, MMP14 and BCL-9L, were potential target genes of miR-125a." (PMID 22768249, 2012). "In the last 3-5 years strong evidence has been gathered demonstrating ErbB3 as a key node for the progression of several cancer types." (PMID 22889873, 2012). "In vitro, these two anti-ErbB3 antibodies modulate the growth rate of cancer cells of different origins and in vivo they show antitumor properties in several xenograft models." (PMID 22889873, 2012). "Cancer-associated fibroblasts were found to secrete neuregulin-1 (NRG-1), which promoted proliferation via phosphorylation of ErbB3 and AKT in AsPC-1 PDAC cells." (PMID 21792199, 2011). "The fusion splices for eight of the 45 PCR validated fusions were not predicted to coincide with ensembl exon boundaries, including CMKLR1-HNF1A and CRADD-ERBB3 involving cancer associated HNF1A and ERBB3." (PMID 21625565, 2011). "AKT and ERK signaling pathways are two key downstream pathways of ERBB3, and play important roles in angiogenesis and cancer development." (PMID 23554686, 2011). "Phosphorylated ErbB3 protein localised to the membrane of carcinoma cells levels with lower expression levels in their cytoplasmic compartment (data not shown)." (PMID 21792199, 2011). "We illustrate the interface related affinity properties of two cancer-related hub proteins: Erbb3, a multi interface, and Raf1, a single interface hub." (PMID 20011507, 2009). "Understanding ErbB3 functions in the normal mammary gland will help to explain its role in cancer etiology and as a modulator of signaling responses to the mammary oncogene ERBB2." (PMID 19019207, 2008). "Increasing evidence suggests that ErbB3 plays a critical role in cancer progression and resistance to therapy." (PMID 18841159, 2008). "Since several studies established that integrin recycling promotes cell migration and cancer cell invasiveness, we reveal a new perspective of how ErbB3 could mechanistically contribute to cell dissemination in part by promoting integrin recycling." (PMID 41348103, 2026).
cancer (continued). "ERBB3 is not often mutated or amplified in cancer; however, the overproduction of ligands is another way that malignancies abnormally activate ERBB receptors, such as through the presence of an autocrine loop between ERBB3 and NRG1." (PMID 41374970, 2025). "ERBB2 amplification was most prevalent in GEC (15.5%), salivary gland (11.8%), bladder (10.9%), uterine (10.3%), and breast (9.9%) cancers, whereas ERBB3 amplification was most prevalent in small bowel (2.4%), uterine (2.2%), GEC (1.9%), biliary tract (1.5%), and ovarian (1.2%) cancers." (PMID 40178042, 2025). "Regarding ERBB3, correlation analyses including data from CTRP associate its expression with resistance to ferroptosis-inducing drugs like Erastin and RSL3, based on AUC curves across various cancers, including gastro-esophageal cell lines." (PMID 40846695, 2025). "ERBB2 mutations were most prevalent in bladder (8.8%), small bowel (7.4%), urinary tract (5.9%), cervical (4.8%), and salivary gland (3.9%) cancers, whereas ERBB3 mutations were most prevalent in small bowel (5.3%), bladder (5.2%), urinary tract (4.0%), GEC (2.3%), and uterine (2.1%) cancers." (PMID 40178042, 2025). "In addition, CDX2-suppressed cancers had a higher prevalence of mutations in several receptor tyrosine kinase genes, including EGFR, ERBB3, ERBB4, RET, and ROS1." (PMID 39452477, 2024). "Nrdp1-mediated ErbB3 degradation inhibited cellular proliferation and motility, while Nrdp1 depletion in BC could accelerate cancer growth by enhancing ErbB2/ErbB3 signaling." (PMID 38835349, 2024). "A logistic regression model, using 5 proteins (ITGB5, TGF-α, TLR3, WIF-1, and ERBB3) with highest AUC values, demonstrated good predictive performance for prognosis of CC patients undergoing immunotherapy and showed potential across different cancer types." (PMID 38835778, 2024). "Cancer therapies targeting ERBB3 are known to be cardiotoxic, while its ligand NRG1 may improve LVventricular contractility in HFrEF." (PMID 39180332, 2024). "Since EGF can bind to receptors other than EGFR, such as ErbB2 (HER2), ErbB3 (HER3), and ErbB4 (HER4) across most cancer contexts, and is a key player in cancer metastasis, it is likely that the EGF-associated mechanisms driving EMT are distinct from those regulating MHC I expression." (PMID 38067396, 2023). "Nevertheless, antibody‐based therapy of cancer has achieved significant success in the last years and MABs against EGFR (cetuximab, panitumumab), ERBB2 (trastuzumab, pertuzumab), and ERBB3 (patritumab, seribantumab, lumretuzumab) are used to treat various type of cancer." (PMID 37341059, 2023). "Cancer tissues had higher ERBB3 expression than normal tissues in 50%–70% of BRCA cases." (PMID 35990843, 2022). "In light of this, we assessed whether Ad-mediated silencing of ErbB3 would lead to inhibition of cancer cell proliferation." (PMID 35806132, 2022). "Since the interactions of ErbB3 with ErbB1 and ErbB2 are critical for oncogenic signaling, it has been anticipated that ErbB1- or ErbB2-overexpressing cancers could be promising targets." (PMID 35806132, 2022). "ErbB3/HER3 overexpression is associated with lung, colon, gastric, and other cancers and has been also found to be responsible for resistance to HER2, IGF1R, and EGFR inhibitors in the treatment of several types of cancers." (PMID 35938171, 2022). "Furthermore, a colony-forming assay was performed to investigate the long-term effect of ErbB3 knockdown on the growth of cancer cells." (PMID 35806132, 2022). "The co-expression of ErbB2 and ErbB3 was reported in different types of cancers." (PMID 35177646, 2022). "Their studies suggested that ERBB3-mediated activation of PI3K/Akt might be a common feature of cancer cells that have c-Met amplification." (PMID 34998412, 2022). "Although less common than ERBB3 amplification, ERBB3 deletion (0.04% frequency) could play a role in how cancer progresses." (PMID 36551663, 2022).